OR14C36 (olfactory receptor family 14 subfamily C member 36)
Description:
Odorant receptor.
Synonyms: OR5BF1
Tractability: Antibody: UniProt places it where antibodies can reach, with medium confidence; UniProt predicts a signal peptide or a membrane-spanning region; its Gene Ontology location is reachable by antibodies, with medium confidence.
Gene: Protein-coding gene on chromosome 1 (248,348,775 to 248,349,713, forward strand). Ensembl gene ENSG00000177174.
Subcellular location: Cell membrane
Pathways (Reactome):
Sensory Perception: Expression and translocation of olfactory receptors
Gene Ontology:
Molecular function: odorant binding; olfactory receptor activity; G protein-coupled receptor activity
Biological process: sensory perception of smell; detection of chemical stimulus involved in sensory perception of smell; G protein-coupled receptor signaling pathway
Cellular component: plasma membrane; membrane
Genetic constraint (gnomAD): Loss-of-function variants: 0 observed, 0.49 expected, observed/expected ratio (o/e) 0, 90% interval 0 to 1.84. That is too few expected variants to judge how well the gene tolerates losing a copy. Missense variants: 396 observed, 398.07 expected, observed/expected ratio (o/e) 0.99, 90% interval 0.92 to 1.08. Synonymous variants: 141 observed, 152.39 expected, observed/expected ratio (o/e) 0.93, 90% interval 0.81 to 1.06.
Homologues: Orthologues: chimpanzee OR14C36 (96% identical), mouse Or14c39 (60% identical), rat Or14c39 (60% identical), mouse Or14c40 (59% identical), mouse Or14c44 (59% identical), rat Or14c39b (59% identical), mouse Or14c43 (58% identical), rat Or14n1 (58% identical), mouse Or14c41 (58% identical), rat Or14c43 (58% identical), mouse Or14c46 (57% identical), rat Or14c40 (57% identical), and 4 more. Paralogues in human: OR14A16 (48% identical), OR14I1 (48% identical), OR14J1 (46% identical), OR14L1 (45% identical), OR14A2 (44% identical), OR14K1 (42% identical), OR5AP2 (42% identical), OR5B12 (41% identical), OR5I1 (40% identical), OR9H1 (40% identical), OR5A1 (40% identical), OR5B21 (40% identical), and 84 more.